PPARG (peroxisome proliferator activated receptor gamma)
Diseases named in the same sentence as PPARG in open-access papers (continued):
Sharing a sentence is not in itself a finding about the gene and the disease.
Hepatic steatosis (continued). "HBx induces lipid accumulation by activating sterol regulatory element-binding protein 1 (SREBP1) and peroxisome proliferator-activated receptor gamma (PPAR-γ) in liver cells, leading to HBV-associated hepatic steatosis." (PMID 36875742, 2023). "In line with this assumption, hepatic overexpression of DGAT2 markedly increased DAG levels in the liver of the transgenic mice and knockdown of MGAT1 expression protected mice from HFD and PPARg-induced hepatic steatosis, respectively." (PMID 37059417, 2023). "In fact, PPARγ is a key up-regulator of hepatic steatosis in HFD-induced obese mice treated with rosiglitazone." (PMID 36837793, 2023). "Furthermore, diosmin promoted browning of iWAT and ameliorated hepatic steatosis with attenuated proinflammatory responses in iWAT and liver, with no apparent adverse effects such as edema or cardiovascular disease risk previously reported in PPARγ full agonist usage." (PMID 36841479, 2023). "For example, in mice with low hepatic expression of PPARγ, rosiglitazone protects against lipid accumulation while in obese mice with elevated PPARγ, rosiglitazone exacerbates hepatic steatosis." (PMID 36837793, 2023). "Hepatic PPARγ independently regulates the liver lipid accumulation in mice, and in recent years PPAR-γ expression has been identified as an additional signaling that modulates the SREBP-1c to trigger hepatic steatosis." (PMID 36675107, 2023). "Several drugs, including thiazolidinediones (peroxisome proliferator-activated receptor gamma (PPARγ) agonists that are insulin sensitizers) are being investigated as therapies to reduce hepatic steatosis, inflammation, and fibrosis." (PMID 36837793, 2023). "The hepatic knockdown of PPARγ-attenuated chronic alcohol feeding induced hepatic steatosis and injury, inhibiting the expression of SREBP-1c." (PMID 37627597, 2023). "In fact, a prior study found that, in diet-induced obese mice, methylation of hepatic interferon regulatory factor 6 (Irf6) reduces hepatic steatosis and metabolic abnormalities by transcriptionally repressing Pparγ." (PMID 37190114, 2023). "For instance, previous studies have shown that exposure to PM2.5 inhibits PPARγ signal transduction, to which subsequent liver damage, such as triglyceride accumulation and hepatic steatosis, can be partly attributed." (PMID 37780625, 2023). "Although PPARγ generally distributes at low levels in the liver, it plays an important role in the induction of liver steatosis via the expression of MGAT 1, a key enzyme in TG synthesis, with increasing its liver content." (PMID 37569481, 2023). "In the course of exploring new therapeutic agents for fatty liver disease, PPARg agonists (such as rosiglitazone) were tested." (PMID 37818230, 2023). "A previous study showed Cd36 null mice are protected from hepatic steatosis induced by Lxr agonists and that Cd36 is a common target of Lxr, as well as Pparγ and pregnane X receptor." (PMID 35406736, 2022). "On the contrary, PPARγ is a well-recognized marker of liver steatosis that allows energy storage through the activation of lipogenic genes." (PMID 36364243, 2022). "It is reported that the expression of PPARγ is specifically upregulated in the liver of HFD-induced mice, and suppression of PPARγ expression reduces fatty liver induced by HFD." (PMID 35432557, 2022). "According to previous research, the phosphorylation of ERK1/2 promotes PPARγ overexpression in the liver, which increases TG accumulation and the development of hepatic steatosis." (PMID 35872979, 2022). "Together, our data reveal a novel role of HMGB1 in alleviating liver steatosis through the repression of the LXRα/PPARγ axis during metabolic stress." (PMID 35333579, 2022). "In regard to hepatic steatosis, Hyp attenuated the lipid accumulation in liver by preserving hepatic lipid and bile acid homeostasis via the regulation of PPARγ, FXR, LXRα, ACC, SREBP, cholesterol 7α-hydroxylase (CYP7A1), and CYP27A1." (PMID 35892639, 2022).
Hepatic steatosis (continued). "Although PPARγ activation in adipose tissue offers a unique method for managing NAFLD, the side effect of activation of PPARγ will be hepatic steatosis." (PMID 36552725, 2022). "In A-ZIP/F-1 mice, disrupting hepatocyte PPARγ reduced hepatic steatosis but worsened hyperlipidemia and muscle insulin resistance." (PMID 36359869, 2022). "The preventive effects of ICAE on fatty liver are concerned with the downregulation of PPARγ and ADRP protein expression in liver." (PMID 35432557, 2022). "It is reported that ADRP is a target gene of PPARγ and is upregulated in liver steatosis in both humans and mice." (PMID 35432557, 2022). "The observation was attributed to mitochondrial dysfunction and impaired lipid metabolism; however, the liver steatosis seems also to be driven by the activities of the peroxisome proliferator-activated receptor-gamma (PPAR-γ)." (PMID 35806442, 2022). "Prenatal exposure to a low-protein diet exhibited a lower expression of PPARγ and hepatic steatosis." (PMID 36359869, 2022). "ADRP is a lipid storage droplet-associated protein and is also upregulated by an HF diet through PPARγ activation, followed by the induction of liver steatosis." (PMID 36140300, 2022). "PPARγ increases the gene expression of essential proteins that support lipid droplet expansion and it is expressed at low levels in normal liver, whereas increased expression of PPARγ is a common feature of hepatic steatosis." (PMID 35592528, 2022). "They reported that the up regulated miR-27a-5p induces fatty liver disease by suppressing the expression of PPARγ." (PMID 35978298, 2022). "The effect of Djulis hull crude extract on hepatic steatosis is likely due to reduced inflammation mediated by PPARγ and enhanced expression levels of proteins involved in fatty acid oxidation mediated by AMPK signaling." (PMID 34829565, 2021). "It has been reported that in a chronic high fat with binge alcohol consumption murine model, inflammation induced through PPARγ upregulation is an independent modulator in the progression toward liver steatosis." (PMID 33662521, 2021). "Overexpression of SHBG, by creating a double transgenic mouse (SHBG-C57BL/ksJ-db/db), in a NAFLD model or in a diet–induced model of hepatic steatosis, significantly reduced liver fat accumulation through PPARγ modulation." (PMID 33854482, 2021). "Our study firstly revealed that G. cambogia and HCA inhibited HFD- and FFA-induced C/EBPα and PPARγ activation by reducing intracellular ROS levels and leading to suppression of lipogenic gene transcription and hepatic steatosis." (PMID 34439474, 2021). "It was reported that ceramide can influence TAG homeostasis, and hepatic steatosis throughout PPARγ, a member of a nuclear hormone superfamily." (PMID 33513874, 2021). "TMP alleviated hepatic steatosis (lipid contents and lipid droplets) in high-fat-fed mice and down-regulated the PPARγ, CD36, and DGAT2 gene levels." (PMID 33807173, 2021). "Here, we found that HFD increased PPARγ expression, and induced liver steatosis, both restored by OEA administration." (PMID 34439537, 2021). "Previous evidence typically demonstrated that FAS and SCD1, PPARγ in an inverse correlation between fatty liver and fibrosis." (PMID 33673073, 2021). "Alcohol can activate the gene expression of PPARγ signaling pathway, which promotes the production of fat, thereby aggravating hepatic steatosis." (PMID 35003311, 2021). "Adenovirus-mediated overexpression of PPARγ2 in hepatocytes increased hepatosteatosis and hepatocyte-specific disruption of PPARγ gene (PPARG) decreased liver steatosis in PPARγ−/− mice." (PMID 34869329, 2021). "Overexpression of PPARγ in hepatocytes increased hepatosteatosis, while hepatocyte-specific disruption of Pparγ gene expression decreased liver steatosis in ob/ob mice." (PMID 34069390, 2021).
Hepatic steatosis (continued). "In another study of high-fat diet mice, H19 lncRNA acts as a sponge to miR-130a to upregulate peroxisome proliferator-activated receptor gamma (Pparg) expression, concomitant with hepatic steatosis." (PMID 35052690, 2021). "PPARγ in the liver plays a role in regulating the homeostasis of triglyceride, leading to hepatic steatosis, but alleviating triglyceride accumulation and insulin resistance in other tissues." (PMID 34443619, 2021). "Collectively, our findings suggest that appropriate functional antagonism of PPARγ is a logical approach to prevent and treat diet-induced liver steatosis and other related metabolic disorders." (PMID 34128467, 2021). "Oxidation of fatty acid and expression of fatty acid transport protein shares a close relationship with nuclear receptor PPARα and PPARγ in liver steatosis." (PMID 33935766, 2021). "A HFD can induce PPARγ expression, which accelerates lipid accumulation and leads to hepatic steatosis in mouse liver cells." (PMID 34684339, 2021). "Because our previous study showed that the Pparγ mRNA expression level, one of the markers of hepatic steatosis, was increased in normal murine hepatocytes transfected with siPhb1, which mimics liver-specific Phb1−/− (unpublished data, under review)." (PMID 34539442, 2021). "Collectively, PPARγ disrupted in adipose tissue contributed to liver steatosis and inflammation progression." (PMID 34943809, 2021). "Several studies also showed that epigenetic changes can regulate the transcription factor peroxisome proliferator-activated receptor γ (PPARγ), which is known as a master regulator of lipogenic genes involved in fatty liver diseases." (PMID 34572442, 2021). "Recent studies revealed HNF1α as a direct transcriptional repressor of PPARγ in the context of hepatic steatosis." (PMID 32235813, 2020). "PPARγ plays a significant role in protecting the liver from inflammation, oxidation, fibrosis, fatty liver and tumours." (PMID 32031298, 2020). "Conversely, muscle- or adipocyte-specific PPARγ deletion promotes hepatic steatosis, which is consistent with the idea that PPARγ activity in adipose, and perhaps muscle, mediates much of Pio's efficacy towards NAFLD." (PMID 32963510, 2020). "Several studies indicated that HBx causes hepatic steatosis in hepatocyte mediated by transcriptional activation of sterol regulatory element-binding protein 1 (SREBP1) and peroxisome proliferator-activated receptor gamma (PPARγ)." (PMID 32317690, 2020). "PPARγ binds to the promoter of CD36 and increases its expression, which is associated with the development of hepatic steatosis." (PMID 32411189, 2020). "Changes similar to the inhibition of hepatic steatosis were observed in the mRNA expressions of four adipogenesis and lipogenesis related genes (PPARγ, C/EBPα, FAS, and aP2) in the HFD + Vehicle- and HFD + LEP-treated groups." (PMID 32521713, 2020). "Genistein administration alleviated hepatic steatosis and apoptosis through the down-regulation of PPARγ and up-regulation of adiponectin expression." (PMID 33383845, 2020). "For example, hepatocellular PPARγ overexpression induces hepatic steatosis, while liver-specific PPARγ disruption prevents hepatic fat accumulation in mouse NAFLD models." (PMID 32963510, 2020). "Whereas increased PPARγ activity within hepatocytes would be expected to contribute to steatosis, the treatment of patients with the PPARγ agonists rosiglitazone or pioglitazone result in reduced hepatic steatosis." (PMID 32660130, 2020). "A recent study also demonstrated that histone H3K4 methyltransferase MLL3/4 is recruited to the PPARγ responsible element of PPARγ2 and its target steatosis genes, stimulating their expression and resulting in hepatic steatosis." (PMID 33167594, 2020). "ATF4 depletion protects mice from high fructose-induced hepatic steatosis by reducing lipogenesis through the reduced hepatic expression of PPARγ, SREBP1c, ACC, and FASN." (PMID 32660130, 2020).
Hepatic steatosis (continued). "As previously was reported by Gonzalez-Periz, RvE1 protects against liver steatosis by improving insulin tolerance and induction of PPARγ and adiponectin." (PMID 33266360, 2020). "Some animal studies have shown that PPARγ overexpression was associated with adipogenic transformation of hepatocytes and the ablation of hepatic PPARγ alleviated hepatic steatosis." (PMID 33383845, 2020). "Genistein also attenuated hepatic steatosis by reducing the PPARγ target gene monoacylglycerol O-acyltransferase 1, mRNA level in apolipoprotein E-deficient (ApoE(−/−)) mice fed a HF diet." (PMID 33383845, 2020). "Emodin has been proved to increase the mRNA level of PPARγ and play a protective role in alcohol-mediated liver steatosis." (PMID 33415161, 2020). "The following contents describe the molecular mechanisms and/or signaling pathways that are regulated by PPARγ, so as to reveal the dysregulation of lipid metabolism in hepatocytes and therefore contribution to fatty liver disease." (PMID 32272794, 2020). "Determining the crucial genetic factors, such as PPARγ, will also provide essential clues in breeding improvement of fatty liver disease-resistant dairy cattle, eventually contributing to sustainable development of dairy industry." (PMID 32272794, 2020). "Discovery and revealing the mechanisms of the important regulatory factors/genes, such as PPARγ, that regulate the pathogenesis of this disease is pertinent and imperative for preventing and treating fatty liver disease in humans and animals." (PMID 32272794, 2020). "The hepatic PPARγ plays a putative role in the progression of fatty liver disease in the NAFLD patients." (PMID 31935815, 2020). "The other proposed mechanisms in improving liver enzymes and fatty liver by curcumin were reducing inflammatory markers, lipid synthesis/accumulation, anthropometric measurements, and oxidative stress, PPARγ activation, and effects on glycolysis." (PMID 30705687, 2019). "Although various studies reported that both FoxO1 and PPARγ stimulated hepatic steatosis, the functional relationship between these two proteins in the context of aging is unclear." (PMID 31246177, 2019). "In genetically and diet-induced obese mice, increased PPARγ expression is involved in hepatic steatosis by increasing the expression of lipogenesis gene." (PMID 31246177, 2019). "The authors concluded that ASX treatment ameliorates high-fat diet-induced hepatic lipid accumulation and hepatic steatosis in mice via differential regulatory actions involving PPARα and PPARγ." (PMID 31018521, 2019). "Recent studies indicated that the PPARγ activation showed a protective effect by increasing SIRT6 expression in animal models of hepatic steatosis and Huntington’s disease (HD)." (PMID 30791908, 2019). "As a transcription factor, PPARγ plays an important role in hepatic steatosis by inducing lipogenesis-related gene expression." (PMID 31246177, 2019). "Because hepatic PPARγ and C/EBPα proteins are known to play a role in the development and maintenance of hepatic steatosis, we assessed the expression levels of these in the liver tissues of HFD-fed Wdr76+/+ and Wdr76−/− mice." (PMID 31873167, 2019). "Conversely, several studies have reported that rosiglitazone promoted HFD-induced liver steatosis in mice, and mice with low hepatic PPARγ expression had a low incidence rate of fatty liver." (PMID 31336903, 2019). "While PPARα activation has been known to alleviate fatty liver by stimulating β-oxidation and reducing lipogenesis, the effect of activated PPARγ on hepatic steatosis is controversial." (PMID 30733541, 2019). "Elimination of PPARγ in the liver of lipoatrophic A-ZIP/F-1 (AZIP) mice had beneficial effects on the hepatic steatosis." (PMID 31121839, 2019). "Accordingly, hepatospecific PPARγ deletion reduced hepatic fat content in mice fed a HFD that developed hepatic steatosis." (PMID 31121839, 2019).
Hepatic steatosis (continued). "PPARγ is involved in regulation of adipogenic differentiation, lipid metabolism, insulin sensitivity and hepatic steatosis." (PMID 30923554, 2019). "IR can upregulate SREBP-1c, ChREBP, and PPARγ to promote hepatic steatosis, which in turn can promote IR by SREBP-1c, ChREBP, and PPARγ." (PMID 30719457, 2019). "PPARγ is required for lipid synthesis, transport, and storage, and its expression is markedly increased in hepatic steatosis." (PMID 31123488, 2019). "Although liver expression of PPARγ is relatively low in basal conditions, its expression is upregulated in fatty liver diseases such as NAFLD, where it induces de novo lipogenesis and lipid accumulation." (PMID 30987128, 2019). "Although liver PPARγ expression is relatively low in basal conditions, it acts as a steatogenic factor and its expression is upregulated in fatty liver diseases such as NAFLD, where it induces de novo lipogenesis and lipid accumulation." (PMID 30987128, 2019). "In the liver, PPARγ expression is normally low but becomes drastically induced as hepatic steatosis develops." (PMID 30566427, 2018). "Simultaneously, PPARγ levels were shown to be upregulated in HFHF rats with severe hepatic steatosis." (PMID 30363947, 2018). "For instance, overexpression of PPARγ leads to hepatic steatosis and hepatocyte-specific knockout of PPARγ reduces hepatic fat content in HFD-fed mice." (PMID 29743883, 2018). "In the present study, KK-Ay mice developed obvious hepatic steatosis, accompanied with elevated expression of PPARγ in the liver, which were significantly reversed by SD-FRE treatment." (PMID 30061831, 2018). "One of the suggested mechanisms in which PPARγ contributes in hepatic steatosis is by enhancing the de novo lipogenesis through stimulating LXR, which in turn activates SREBP-1c, ChREBP, FAS, and ACC." (PMID 30096951, 2018). "It was found that rosiglitazone, a PPARγ agonist, seriously increases hepatic steatosis, due to its elevated hepatic expression of PPARγ, while deleting PPARγ in liver cells protected mice against hepatic steatosis induced by high-fat diet." (PMID 30096951, 2018). "Conversely, a high level of PPARγ in mouse liver resulted in exacerbated hepatic steatosis through activating lipogenic genes, thereby increasing de novo lipogenesis and hepatic triglyceride content." (PMID 30061831, 2018). "Rosiglitazone (RGZ), an agonist of peroxisome proliferator-activated receptor gamma (PPARγ), plays an important role in protecting against fatty liver disease." (PMID 29535637, 2018). "This cell model was qualified as an in vitro hepatic steatosis model for further silent RNA assay to knockdown of PPARα and PPARγ." (PMID 28831172, 2017). "The coactivator mediator subunit MED1 is the only coactivator that is required for PPARγ-stimulated adipogenic hepatic steatosis in mice." (PMID 28611668, 2017). "Hepatic steatosis is coordinated by transcriptional factors such as peroxisome proliferator-activated receptor γ (PPARγ), sterol regulatory element-binding protein 1c (SREBP1c) and carbohydrate-responsive element-binding protein (ChREBP)." (PMID 28081181, 2017). "In accordance with body weight reduction, PPARγ antagonism markedly reduced hepatic steatosis in both RORαf/f and RORαLKO mice." (PMID 28757615, 2017). "As reported, the coactivator mediator subunit MED1 is the only coactivator required for PPARγ-stimulated hepatic steatosis." (PMID 28611668, 2017). "Our study evidenced an important clue that pioglitazone attenuated hepatic steatosis by amplifying cytosolic lipolysis, β-oxidation, and lipophagy, which were differentially mediated by both PPARα and PPARγ." (PMID 28831172, 2017). "Pioglitazone, exhibiting dual PPARα/PPARγ agonist, has been established to improve insulin sensitivity and attenuate hepatic steatosis in human studies." (PMID 28831172, 2017).